TRIM31 (tripartite motif containing 31)
Diseases named in the same sentence as TRIM31 in open-access papers (continued):
Sharing a sentence is not in itself a finding about the gene and the disease.
cancer (continued). "In this review, we comprehensively overview the structure, expression and regulation of TRIM31 in cancer." (PMID 36620540, 2022). "According to the findings presented, the overexpression of TRIM31 had a role in the development, invasion, and metastasis of cancer, as well as resistance to chemotherapy." (PMID 35054365, 2022). "Studies in cancer have indicated that TRIM31 acts as an oncogene in the progression of several tumors." (PMID 34650049, 2021). "Recent studies have reported that TRIM31 acts as an E3 ubiquitin ligase and is involved in a wide range of biological processes, including autophagy, inflammation, antiviral immunity, and cancer." (PMID 34650049, 2021). "TRIM31 is a cancer-related TRIM protein that has been observed to exert oncogenic activity in several types of cancers." (PMID 32232394, 2020). "Whilst TRIM31 is commonly overexpressed in cancers, the mechanism by which TRIM31 is overexpressed remains unknown." (PMID 35054365, 2022). "In this review, in addition to accumulating recent corroborations that endorse this dual role of TRIM31 in cancer, we also discuss the emerging role of TRIM31 in innate immunity, inflammation and autophagy and its growing sphere of influence across multiple other human pathologies." (PMID 36620540, 2022). "The different target proteins of TRIM31 may decide the tumor promoter or tumor suppressor of TRIM31 in cancer." (PMID 36620540, 2022). "Here, we will discuss why TRIM31 can promote or inhibit cancer from the following aspects." (PMID 36620540, 2022). "Recently, studies have shown that TRIM31 is an oncogene in various cancers." (PMID 36620540, 2022). "Therefore, discovering new target proteins of TRIM31 is necessary to further understand the role of TRIM31 in cancer." (PMID 36620540, 2022). "Studies have shown that the TRIM31 isoforms have different biological roles in cancer." (PMID 36620540, 2022). "To date, the clinical correlation of TRIM31 in cancer is still elusive." (PMID 36620540, 2022). "In CRC, the high expression of TRIM31 promotes cancer invasion and metastasis." (PMID 35054365, 2022). "These seemingly contradictory observations may be related to the different timing and versatile roles that TRIM31 has in cancer initiation, tumor progression, and the development of drug resistance." (PMID 33311639, 2020). "Given its involvement in these cancers, we speculated that TRIM31 might represent therapeutic target in AML." (PMID 32232394, 2020). "We speculate that TRIM31 may be involved in viral stimulation of innate immune responses, which is an early event preceding cancer initiation to maintain tissue homeostasis." (PMID 33311639, 2020). "Considering the oncogenic roles of TRIM31 in these types of cancers, we speculated that TRIM31 might exhibit similar biological functions in AML." (PMID 32232394, 2020). "However, the clinical correlation of TRIM31 with cancer is still elusive." (PMID 40919166, 2025). "However, TRIM31 exhibits contradictory functions in the progression of cancer." (PMID 38978046, 2024). "Finally, a better understanding of the dual role of TRIM31 in cancer may provide new therapeutic strategies aimed at inhibiting the cancer-promoting effects of TRIM31 without affecting its tumor suppressor effects." (PMID 36620540, 2022). "Therefore, the differential expression of TRIM31 isoforms may lead to the different roles of TRIM31 in cancer." (PMID 36620540, 2022). "XAF1, TRIM31, G0S2 and IFI6 have known roles in apoptosis or its prevention, while PAX7, TRIM31 and PNMA8A are involved in cell development/development of cancer." (PMID 38990812, 2024). "Our transcriptomic data align with existing studies that have identified genes like NPTX1, TRIM31, and CD82/KAI1 as potential therapeutic targets in various cancers." (PMID 37958599, 2023).
cancer (continued). "Besides the expression of TMPRSS2, TMPRSS4, and TRIM31 in GI cancers, we have analysed the expression of these genes in all cancers, and we have found that the expression of these genes is more upregulated in majority of GI cancers than individual other cancer types." (PMID 35970857, 2022). "As a result, three genes, SH3BGRL2, TJP3 and TRIM31, were positively correlated with TMPRSS2 and TMPRSS4 for all cancer cell lines and showed distinct differential expression profiles across GI solid tumors." (PMID 35970857, 2022). "TRIM31 is a member of the TRIM family, and the proteins of this family have been reported to play important roles in cancer progression." (PMID 34650049, 2021). "Two non-human leukocyte antigen (HLA) genes are E3 ubiquitin ligases, TRIM31 and TRIM39, having a role in the innate immune response and implicating the importance of host Epstein-Barr virus interactions in this cancer." (PMID 33311639, 2020). "In recent years, many research studies have shown that TRIM family proteins, such as TRIM3, TRIM11, TRIM19, TRIM31, TRIM44 and TRIM59 have been demonstrated to serve a significant role in the tumorigenesis and progression of numerous cancer types." (PMID 30484263, 2019). "In addition, TRIM31, TRIM32, and TRIM47 were reported to play a role in the AKT signaling pathway in cancer." (PMID 36261847, 2022). "MT2A and TRIM31 which were engaged in IFN-γ signaling, CDC6, SGK1 and PTP4A1 genes, presented a homogeneous expression pattern in both test and Validation datasets, although our results were contradictory to other studies in different cancers." (PMID 34249670, 2021). "Using the 5 patients with both normal and cancer cells profiled, we estimated the frequency of inactivation of all 56 colon-specific TFs across the 5 patients, which revealed that CDX2 and TRIM31 were inactivated in 80% of the patients, whereas ATOH1, HNF4A, CDX1, and TBX10 were inactivated in 60%." (PMID 33083012, 2020). "Similarly, Tripartite motif containing 31 (TRIM31), reported to suppress colony-forming units (CFU) formation of cancer cells in vitro, was highly upregulated in T24MshPFN1 cells (5.36-fold)." (PMID 27683119, 2016). "We found that TRIM31 expression was markedly lower in cancer tissues than in normal breast tissues." (PMID 34650049, 2021).
tumor (19 papers, 2016 to 2026). "Our analysis showed that decreased expression of TRIM31 was associated with larger tumor size, higher Ki67 expression, advanced TNM stage, advanced histological grade, and lymph node invasion." (PMID 34650049, 2021). "In addition, TRIM31 deficiency-mediated increased tumor growth was abolished by the knockout of MDM2." (PMID 34650049, 2021). "Moreover, we further investigated the effect of MDM2 on TRIM31-mediated tumor growth, TRIM31-deficient MCF7 cells were introduced sgRNA targeting MDM2." (PMID 34650049, 2021). "Moreover, low TRIM31 expression was associated with larger tumor size, higher Ki67 expression, advanced TNM stage, advanced histological grade, and lymph node invasion." (PMID 34650049, 2021). "Recent studies have shown that TRIM31 plays a role in promoting tumor progression in a variety of tumors, such as liver cancer, colon cancer, and bladder cancer." (PMID 40919166, 2025). "Both Western blotting and immunohistochemistry (IHC) analyses revealed a significant upregulation of TRIM31 in ulcerative and tumor tissues, with the highest expression observed in tumors." (PMID 40819060, 2025). "In vivo, a subcutaneous xenograft model using BALB/c nude mice confirmed that TRIM31 facilitated Axin1 degradation to promote tumor growth and progression." (PMID 39768197, 2024). "The suppression of miR-876-3p/TRIM31 axis was related to the impeded AML cell growth, indicated the role of TRIM31 in tumor cell cycle." (PMID 38978046, 2024). "The knockdown of TRIM31 reduced the proliferation of GC tumor cells and negatively regulated the cell cycle displayed by the decrease of CylclinD1 and CDK2." (PMID 38978046, 2024). "MiR-551b functions through the suppression of forkhead box O3 (FOXO3) and tripartite motif containing 31 (TRIM31), two important tumor suppressors." (PMID 34512721, 2021). "Multivariate Cox regression showed that age, clinical stage, and tumor TRIM31 status were independent prognostic indicators of NPC survival." (PMID 33311639, 2020). "Further analysis suggested that miR-551b functioned through the suppression of Foxo3 and TRIM31, two important tumor suppressors." (PMID 27743201, 2016). "Furthermore, results from the mouse xenograft tumor model showed that CRC cell-derived tumors with TRIM31 knockdown grew more slowly and had lighter tumor weights compared to control cells." (PMID 40819060, 2025). "While, suppression of TRIM31 expression may trigger oxidative stress in tumor cells, leading to apoptosis." (PMID 38978046, 2024). "In our study, the IC50 of cisplatin and docetaxel were higher in TRIM31-high group, indicated high expression of TRIM31 may contributed to the resistance of cisplatin and docetaxel in GC tumor cells." (PMID 38978046, 2024). "TRIM31 was significantly overexpressed in several tumor types, including GC." (PMID 37973999, 2023). "Hence, our study presented a tumor-promoting role of TRIM31 and a connection with Axin1 in GC, supporting a critical role of TRIM31-Axin1-β-catenin axis in GC development." (PMID 37973999, 2023). "In addition, we also analyzed the effect of MDM2 overexpression on Trim31-mediated tumor growth suppression." (PMID 34650049, 2021). "Moreover, we found that the RING and coiled-coil (C–C) domains of TRIM31 were essential for its tumor suppressor function." (PMID 34650049, 2021). "Apart from its tumor-promoting function, TRIM31 can also exert a tumor suppressor function." (PMID 34650049, 2021).
tumor (continued). "The median overall survival (OS) of NPC patients from the tumor TRIM31 (+++) positive group (median OS 32 months) was significantly shorter compared to those from the tumor TRIM31 (++) group (median OS 44 months), TRIM (+) group (median OS 76 months) and TRIM negative group (median OS NR months)." (PMID 33311639, 2020). "The data suggested that the mediation of Foxo3 and TRIM31 by miR-551b was occurring in vivo and might play a key role in the observed impacts of miR-551b on tumor growth." (PMID 27743201, 2016). "Our results suggest a tumor-suppressive role of TRIM31 in OVCa cells in response to miR-551b." (PMID 27743201, 2016). "In addition, H&E and IHC staining revealed that the expression level of Ki67 was much lower in tumor tissues derived from CRC cells with TRIM31 knockdown, while the expression level of Ki67 was significantly higher in tumor tissues derived from CRC cells that overexpress TRIM31." (PMID 40819060, 2025). "Knockdown of TRIM31 expression led to the suppression of CRC cell proliferation and migration in vitro, tumor formation and metastatic ability in vivo." (PMID 40819060, 2025). "In contrast, exogenous overexpression of TRIM31 promoted the growth of xenograft tumors from CRC cells, resulting in heavier tumor weights." (PMID 40819060, 2025). "TRIM31 belongs to the tripartite motif-containing or RING, B-box, and coiled-coil family; it acts as a tumor promoter and has been shown to promote HCC progression." (PMID 35082931, 2022). "Therefore, TRIM31 may act as a tumor suppressor in the early stage of the tumor." (PMID 36620540, 2022). "Among these, TRIM24, TRIM26 were identified as tumor suppressors in the development of HCC, whereas TRIM31 was identified as a tumor promoter for HCC5,15,19." (PMID 29789583, 2018). "However, in the present study, we demonstrated that TRIM31 knockdown markedly suppressed the proliferative and invasive capabilities of CRC cells in vitro, as well as tumor growth and metastasis in vivo." (PMID 40819060, 2025). "Xenograft mice showed decreased tumor growth and the downregulation of TRIM31 and AKT, indicating that exosomal miR-551b-3p could be a tumor suppressor." (PMID 37237523, 2023). "We found that TRIM31 up-regulation significantly delayed tumor formation, while TRIM31-C36A mutant failed to suppress tumor growth." (PMID 34650049, 2021). "In addition, EIF3d, UBR5, BRD4, TRIM31 and LINC00152 are demonstrated to contribute to cell growth or tumor metastasis of GBC cells via PI3K/AKT pathway." (PMID 32333246, 2020). "Notably, TRIM31 (logFC = 1.14), ANXA1 (logFC = 1.05), GBP1 (logFC = 1.01), BIRC3 (logFC = 0.99), APOL1 (logFC = 0.97), IL18 (logFC = 0.94), ANXA2 (logFC = 0.89), BHLHE40 (logFC = 0.83), and EPHA2 (logFC = 0.75) exhibited significant upregulation in tumour tissues." (PMID 38254861, 2024).
metabolic disorders (5 papers, 2018 to 2026). "Collectively, our findings identify the TRIM31/Nrf2 axis as a key molecular switch governing POMC+ neuronal loss, hypothalamic injury and consequent peripheral metabolic disorders triggered by long-term PM2.5 exposure." (PMID 41514067, 2026). "Finally, these obtained findings encourage Trim31 as a feasible therapeutical target for NAFLD/NASH and associated-metabolic disorders which might be accountable to diagnosis and therapeutic schemes." (PMID 35217669, 2022). "Therefore, we speculated that TRIM31 deficiency could facilitate NLRP3 inflammasome activation and then have an important role in the development of metabolic disorders." (PMID 29497383, 2018). "The current findings suggest that Trim31 is an endogenous inhibitor of Rhbdf2 and downstream cascades in the pathogenic process of steatohepatitis and that it may serve as a feasible therapeutical target for the treatment of NAFLD/NASH and associated metabolic disorders." (PMID 35217669, 2022). "Here, we investigated whether TRIM31 in POMC+ neurons mediates PM2.5-induced hypothalamic injury and peripheral metabolic disorders in mice subjected to 24-week PM2.5 exposure." (PMID 41514067, 2026). "Studies have found that TRIM31 is a key inhibitor of MAFLD and metabolic disorders." (PMID 37867509, 2023). "Our results indicate that Trim31 is a key suppressor of NAFLD/NASH and metabolic disorders and may serve as a molecular target for the treatment of these diseases." (PMID 35217669, 2022).
infection (4 papers, 2021 to 2025). The state of being infected such as from the introduction of a foreign agent such as serum, vaccine, antigenic substance or organism. "While Trim31−/− mice manifested a massive loss of weight after infection with C. albicans and finally died of infection, Trim31+/+ mice showed moderate loss of weight, with 45% survival and recovery." (PMID 34362877, 2021). "After 5 days of infection with C. albicans, real-time PCR assay showed that expression of the genes encoding Ifng, Il17a, and Il17f was attenuated in the kidneys from Trim31−/− mice compared to Trim31+/+ mice." (PMID 34362877, 2021). "To further elucidate the function of TRIM31 in anti-fungal immunity, then we assessed the fungal loads in mice at 5 days after infection." (PMID 34362877, 2021). "At early time points of C. albicans infection, Trim31−/− mice showed significantly reduced secretion of IL-6, TNF-α, IL-12, CXCL1, and CXCL2 in their serum at 24 h post-infection as compared with Trim31+/+ mice." (PMID 34362877, 2021). "Consistently, Trim31−/− mice also had lower levels of IL-6 and TNF-α in the homogenates of kidney and liver after 5 days of infection with C. albicans." (PMID 34362877, 2021). "Using this approach, we found three ISGs that restricted infection: IRF1, TRIM31, and RARRES3." (PMID 34871166, 2021). "However, in IAV-infected cells, the fraction of TRIM31 on mitochondria was not increased; rather, it was decreased following infection with IAV." (PMID 41294327, 2025).
bacterial infection (2 papers, 2022 to 2025). "Second, the Basal.MUC16 cluster showed a significant increase (adjusted p < 0.05) in genes associated with bacterial infection (PDZD3, SFTPA2, PIK3C2B), cytokine signaling (TRIM31, SERPINB2), and apoptosis (BCL2L15, VIL1)." (PMID 39935174, 2025). "Therefore, it was inferred that TRIM31 plays essential roles in restricting invasive bacterial infection in intestinal epithelial cells by promoting autophagy, which can affect gut microbes and lead to IBD in pathological cases." (PMID 35373402, 2022). "This is attributed to the specific interaction between TRIM31 and the bacterial receptor NDP52, which induces protective autophagy against invasive bacterial infection or other normal commensal bacteria." (PMID 35373402, 2022).
psychiatric disorder (2 papers, 2011 to 2022). A disorder characterized by behavioral and/or psychological abnormalities, often accompanied by physical symptoms. "Studies have shown that the TRIM31 gene was associated with intelligence only in the background of a psychiatric disorder." (PMID 35907915, 2022). "In addition, this study did provide tentative support for a role of the ATXN1 and TRIM31 genes in previously associated linkage areas for intelligence in the context of a psychiatric disorder, that is, ADHD." (PMID 21302343, 2011). "Associations between intelligence and SNPs in the ATXN1 and TRIM31 genes and in three genomic locations showed replicated association, but only in the samples ascertained for ADHD, suggesting that these genetic variants become particularly relevant to IQ on the background of a psychiatric disorder." (PMID 21302343, 2011).
colorectal (1 paper, 2025). "Our findings indicate that TRIM31 may be an important factor driving colorectal carcinogenesis, providing a potential target for intervention in CRC targeted therapy." (PMID 40819060, 2025).
GI tumors (1 paper, 2022). "Given that the co-expression analysis with TMPRSS2-TMPRSS4 resulted in a positive correlation with TRIM31 in all GI samples, we further investigated the functional role of TRIM31 in GI tumors." (PMID 35970857, 2022). "Further, our findings also demonstrate that TRIM31 expression is upregulated in gastrointestinal tumors, while the inhibition of TRIM31 significantly altered viral replication and viral processes associated with cellular pathways in gastrointestinal cancer samples." (PMID 35970857, 2022). "There was also significant positive correlation of TRIM31 with TMPRSS2 and TMPRSS4 gene pair in all GI tumor samples." (PMID 35970857, 2022).
TRIM31 also shares sentences with these, for which no sentence is quoted: diabetes (2 papers); Obesity (2); age-related macular degeneration (1); atrial fibrillation (1); attention deficit-hyperactivity disorder (1); endometrial adenocarcinomas (1); Glucose intolerance (1); glucose metabolism disorder (1); immune diseases (1); intestinal polyp (1); nasopharyngeal neoplasm (1); nonalcoholic steatohepatitis (1); osteosarcoma (1); Parkinson disease (1); periodontitis (1); rectal cancer (1); reflux esophagitis (1); rheumatoid arthritis (1); schizophrenia (1); Sepsis (1); Stroke (1); vascular disorder (1).